SHPK (sedoheptulokinase)
Description:
Acts as a modulator of macrophage activation through control of glucose metabolism.
Synonyms: SHK; CARKL
Tractability: PROTAC: ubiquitination databases record sites on it; its protein half-life has been measured.
Gene: Protein-coding gene on chromosome 17 (3,608,240 to 3,636,250, reverse strand). Ensembl gene ENSG00000197417.
Subcellular location: Cytoplasm
Subcellular location (Human Protein Atlas): Nuclear speckles; Nucleoplasm
Pathways (Reactome):
Metabolism: Pentose phosphate pathway
Gene Ontology:
Molecular function: protein binding; sedoheptulokinase activity; kinase activity
Biological process: carbohydrate metabolic process; cellular response to lipopolysaccharide; phosphorylation; cellular response to interleukin-13; cellular response to interleukin-4; pentose-phosphate shunt; pentose-phosphate shunt, non-oxidative branch; regulation of inflammatory response; regulation of macrophage activation
Cellular component: cytoplasm; cytosol
Genetic constraint (gnomAD): Loss-of-function variants: 52 observed, 47.81 expected, observed/expected ratio (o/e) 1.09, 90% interval 0.87 to 1.37. The upper end of that interval is the gene's LOEUF score, 1.37, which puts it in group 5 of 6, group 1 being the genes least tolerant of losing a copy. Missense variants: 668 observed, 667.66 expected, observed/expected ratio (o/e) 1, 90% interval 0.94 to 1.07. Synonymous variants: 290 observed, 282.11 expected, observed/expected ratio (o/e) 1.03, 90% interval 0.93 to 1.13.
Homologues: Orthologues: chimpanzee SHPK (99% identical), macaque SHPK (96% identical), pig SHPK (88% identical), mouse Shpk (87% identical), dog SHPK (86% identical), rat Shpk (85% identical), guinea pig SHPK (85% identical), rabbit SHPK (74% identical), tropical clawed frog shpk (60% identical), zebrafish shpk (55% identical). Paralogues in human: FGGY (22% identical), GK (17% identical), GK3 (17% identical), GK2 (17% identical), GK5 (13% identical), XYLB (13% identical).
Diseases named in the same sentence as SHPK in open-access papers:
SHPK is named in the same sentence as 36 diseases in open-access papers, as found by Europe PMC text mining. Sharing a sentence is not in itself a finding about the gene and the disease. The quoted sentences say what the papers report.
cystinosis (2 papers, 2015 to 2019). Cystinosis is a metabolic disease characterized by an accumulation of cystine inside the lysosomes, causing damage in different organs and tissues, particularly in the kidneys and eyes. "As the 57-kb deletion encompasses CARKL/SHPK encoding sedoheptulokinas enzyme, a recent study has also suggested measuring activity of the encoded sedoheptulokinas enzyme if cystinosis is suspected." (PMID 30949462, 2019).
astrocytomas (1 paper, 2022). "In particular, SHPK was highest in GBM, then in oligodendrogliomas, and significantly lower in astrocytomas." (PMID 35682658, 2022).
glioma (1 paper, 2022). A benign or malignant brain and spinal cord tumor that arises from glial cells (astrocytes, oligodendrocytes, ependymal cells). "The immunohistochemistry data in the HPA database reveal that the immunoreactive score (IRS) of SHPK was significantly higher in glioma tissues (both low- and high-grade gliomas) than in the normal cerebral cortex tissues." (PMID 35682658, 2022). "In addition, a significant overexpression of SHPK protein in gliomas compared with normal tissues was found." (PMID 35682658, 2022).
lysosomal storage disease (1 paper, 2019). A metabolic disorder caused by mutations in proteins critical for lysosomal function, including lysosomal enzymes, lysosomal integral membrane proteins, and proteins involved in the post-translational modification and trafficking of lysosomal proteins. "The human homolog SHPK has been linked to a lysosomal storage disease." (PMID 30885922, 2019).
tumor (6 papers, 2013 to 2025). "Therefore, one could hypothesise that a decrease in ceramide level due to acid sphingomyelinase deficiency with conserved SHPK and ceramide kinase activities would lead to an imbalance in favour of S1P and C1P and a subsequent pro-tumour effect." (PMID 34768550, 2021). "With this work, we want to draw attention to the importance of the increased production of S7P by SHPK by correlating the expression of this enzyme with progression and tumor aggressiveness in GBM." (PMID 35682658, 2022). "This work highlights for the first time the importance of SHPK in GBM for tumor progression and proposes this enzyme and the nonoxidative PPP as possible therapeutic targets." (PMID 35682658, 2022). "SHPK mRNA expression was significantly higher in tumor tissues than in nontumor tissues and among different histologies." (PMID 35682658, 2022).
infection (3 papers, 2015 to 2024). The state of being infected such as from the introduction of a foreign agent such as serum, vaccine, antigenic substance or organism. "Recently SHPK [formerly carbohydrate kinase- like (CARKL)] has been identified as a modulator of macrophage regulation during LPS-induced infection." (PMID 25243985, 2015).
SHPK also shares sentences with these, for which no sentence is quoted: autoimmune disease (12 papers); Obesity (6); Autoimmunity (3); cancer (2); experimental autoimmune encephalomyelitis (2); glioblastoma (2); Insulin resistance (2); psoriasis (2); rheumatoid arthritis (2); allergic asthma (1); brain edema (1); brain tumor (1); cholangiocarcinoma (1); epilepsy (1); Hepatic steatosis (1); influenza (1); injury (1); ischemic stroke (1); liver diseases (1); lupus (1); metabolic disorders (1); nematode infections (1); neurodegenerative disease (1); oligodendroglioma (1); parasite infection (1); prostate carcinoma (1); psoriatic arthritis (1); Sézary syndrome (1); Stroke (1); Type I diabetes (1).